SOCS1 (suppressor of cytokine signaling 1)
Diseases named in the same sentence as SOCS1 in open-access papers (continued):
Sharing a sentence is not in itself a finding about the gene and the disease.
in situ ductal carcinoma (1 paper, 2003). "SOCS-1 gene expression increased in the cancerous ducts (+22% vs normal ducts, P<0.05) and in the reactive stromal area (+104% vs adjacent connective tissue, P<0.01) of sections obtained from patients with in situ ductal carcinoma." (PMID 12888825, 2003).
intestinal inflammation (1 paper, 2016). "We also clarified that curcumin can induce SOCS-1 in TNBS-induced intestinal inflammation." (PMID 27544348, 2016). "However, whether the effect of curcumin on anti-inflammatory activities in TNBS-induced intestinal inflammation is mediated by STAT1 and SOCS-1 is less known." (PMID 27544348, 2016).
intestinal tumours (1 paper, 2019). "Specifically, Socs1−/− mice spontaneously develop intestinal tumours in an IFNγ/STAT1-dependent manner, suggesting that SOCS1 controls the chronic inflammatory JAK/STAT1 signalling needed for CRC development." (PMID 31091767, 2019).
invasive carcinoma (1 paper, 2003). A carcinoma that is not confined to the epithelium, and has spread to the surrounding stroma. "Since SOCS-1 methylation becomes manifest only at the invasive carcinoma stage, detection of methylated SOCS-1 may aid in the early detection of invasive pancreatic adenocarcinoma." (PMID 12865927, 2003). "None of the 20 benign or borderline IPMNs without an associated invasive carcinoma harboured SOCS-1 methylation." (PMID 12865927, 2003).
Kawasaki disease (1 paper, 2021). A rare inflammatory disease characterized by an acute febrile, systemic, self-limiting, medium-vessel vasculitis primarily affecting children. "WES analyses did not reveal any variants in SOCS1 or other IFN-related genes but identified 12 rare potentially disease-causing variants with diverse functions in autophagy, Kawasaki disease, viral restriction, and immune responses." (PMID 34531865, 2021).
laryngeal squamous cell carcinoma (1 paper, 2013). A squamous cell carcinoma that arises from the larynx. "This study aims to investigate the expression and function of miR-155 in laryngeal squamous cell carcinoma (LSCC), the relationship between miR-155 and its downstream target suppressor of cytokine signaling 1 (SOCS1)-STAT3 pathway, and the related clinicopathological factors." (PMID 23437123, 2013).
lipid metabolism disorders (1 paper, 2024). "Overall, a lack of Thr hinders the initiation of the JAK-STAT pathway, diminishing the propagation of the feedback-controlled signals SOCS1 and SOCS2 mRNA, potentially causing irregular downstream gene expression associated with lipid metabolism and lipid metabolism disorders." (PMID 39125712, 2024).
lymphopenia (1 paper, 2024). Reduction in the number of lymphocytes. "In contrast to murine SOCS1 deficiency, so far described SOCS1-haploinsufficient (HI) patients generally do not exhibit lymphopenia or specific impairments in lymphocyte differentiation." (PMID 38711523, 2024).
metastasis (1 paper, 2021). The spread or migration of cancer cells from one part of the body (where they first appeared) to another. "Moreover, SOCS1, SOCS2, and CISH were associated with lymphatic metastasis, and SOCS1-7 was associated with distant metastasis in KIRC." (PMID 34926570, 2021).
metastatic tumors (1 paper, 2018). "In mouse models having metastatic tumors, none of the SOCS1-expressing mice had macro metastasis, unlike the controls, suggesting a role for SOCS1 in metastasis suppression." (PMID 30558204, 2018).
migraine (1 paper, 2023). "A larger study of epigenetic changes in SH2D5, NPTX2, COMT, GIT2, ZNF234, and SOCS1 genes is necessary to understand the processes of migraine chronicity and MOH development." (PMID 37298078, 2023). "One study showed that methylation of some CpG sites of COMT, GIT2, ZNF234, and SOCS1 genes could be important for drug addiction and transformation of migraine into MOH, but studies on larger patient cohorts are needed to fully explore this issue." (PMID 37298078, 2023).
monoclonal gammopathy of undetermined significance (1 paper, 2017). "Finally, it was suggested that aberrant methylation of some genes, such as SHP-1 and SOCS-1, helps the progression from monoclonal gammopathy of undetermined significance (MGUS) to MM." (PMID 28369102, 2017).
monocytic leukemia (1 paper, 2025). "Suppressor of cytokine signaling 1 (Socs1), a pivotal member of the SOCS family, was initially identified within the secretory apparatus of IL-6-stimulated M1 mouse monocytic leukemia cells." (PMID 41164311, 2025).
myocardial infarction (1 paper, 2020). Gross necrosis of the myocardium, as a result of interruption of the blood supply to the area, as in coronary thrombosis. "Firstly, inhibition of miR‐155 decreases myocardial infarction (MI)‐induced sympathetic neural remodeling by repressing M1 polarization‐dependent on the SOCS1/NF‐κB pathway." (PMID 33080104, 2020).
Neonatal sepsis (1 paper, 2020). Systemic inflammatory response to infection in newborn babies. "The role of SOCS1 and SOCS3 for immunomodulation during neonatal sepsis warrants further investigation." (PMID 32479514, 2020). "Although the direct mechanisms of the SOCS family of proteins have not been established for neonatal sepsis, our findings suggest a potential role for SOCS1 and SOCS3 in dampening interferon responses." (PMID 32479514, 2020).
nonalcoholic steatohepatitis (1 paper, 2020). "The purpose of this study was to investigate the effects of Qutan Huoxue Formula (QHF) on liver injury in mice with nonalcoholic steatohepatitis (NASH) by upregulating SOCS1 to inhibit the TLR4/NF-κB signaling pathway." (PMID 33293985, 2020).
papillary thyroid carcinoma (1 paper, 2021). "Furthermore, TRIM14 promoted papillary thyroid carcinoma cell proliferation via the interaction with SOCS1, a negative regulator of the STAT3 activation." (PMID 33982666, 2021).
periapical granuloma (1 paper, 2025). Chronic nonsuppurative inflammation of periapical tissue resulting from irritation following pulp disease or endodontic treatment. "Immunohistochemical analysis showed strong positivity for SOCS-1 and IL-1β in the lesions classified as periapical cyst, while the lesions diagnosed as periapical granuloma were not labelled." (PMID 41388504, 2025).
Peutz-Jeghers syndrome (1 paper, 2003). An autosomal dominant disorder caused by pathogenic variants in the STK11 gene, characterized by hamartomatous polyps in the gastrointestinal tract, mucocutaneous pigmentation and increased risk of GI and extra-GI malignancies. "One of these two patients with methylated SOCS-1 in their cancer was a patient with Peutz-Jeghers syndrome." (PMID 12865927, 2003).
pituitary adenomas (1 paper, 2025). "Another gene with notable findings was SOCS-1, which was associated with non-functioning pituitary adenomas across multiple modalities, including methylation-specific PCR (MSP) and EPIC array." (PMID 39859246, 2025).
pneumoniae (1 paper, 2023). "Although this can result in hypercytokinemia, Gal-3 downregulation of SOCS1 expression enables a strong cytokine response, which is necessary for an effective antimicrobial defense against S. pneumonia." (PMID 37298569, 2023).
polyarthritis (1 paper, 2025). "SOCS1 encodes a negative regulator of STAT signaling, and patients with SOCS1 haploinsufficiency present with autoimmune cytopenias, SLE, and polyarthritis, and other autoimmune manifestations." (PMID 40842819, 2025).
polycystic kidney disease (1 paper, 2016). A usually autosomal dominant and less frequently autosomal recessive genetic disorder characterized by the presence of numerous cysts in the kidneys leading to end-stage renal failure. "While ablation of IFNγ prevents the neonatal disease seen in Socs1-/- mice, mice lacking both SOCS1 and IFNγ nevertheless succumb in adult life to polycystic kidney disease and/or a range of inflammatory lesions." (PMID 27583437, 2016).
posterior uveitis (1 paper, 2016). Inflammation of the choroid as well as the retina and vitreous body. "Topical administration of SOCS1-KIR ameliorated acute and chronic posterior uveitis by inhibiting Th17 cells and the recruitment of inflammatory cells into retina while promoting expansion of IL-10-producing Tregs." (PMID 27703302, 2016).
pressure ulcer (1 paper, 2023). "In this study, key regulators of wound healing, SOCS-1, -3, and -5, were combined to maximize the regenerative potential of ADMSCs in pressure ulcer treatments." (PMID 37508509, 2023). "In this study, we co-transfected ADMSCs with SOCS-1, -3, -5, and -com genes, which were then injected into a pressure ulcer mouse model." (PMID 37508509, 2023). "SOCS-1, -3, -5, and -com genes were transfected into ADMSCs to design ADMSCs as highly functional cells that are more effective in treating pressure ulcers in preclinical and clinical trials." (PMID 37508509, 2023).
primary cutaneous lymphoma (1 paper, 2024). Cutaneous lymphoma is a heterogeneous entity with respect to its clinical and pathological features, evolutive profile, prognosis, molecular etiology and response to therapy. "Although detection of mutation in the tumor suppressor SOCS1 gene stands as one of the most prevalent genetic alterations in MF, this genetic abnormality is also shared by other primary cutaneous lymphomas." (PMID 39091627, 2024).
rhabdomyosarcoma (1 paper, 2022). A rare aggressive malignant mesenchymal neoplasm arising from skeletal muscle. "We confirmed induction of SOCS1 and 3 in rhabdomyosarcoma (RD) cells, and this induction was suppressed by pJAK2 peptide." (PMID 35799776, 2022).
rheumatic heart disease (1 paper, 2021). An autoinflammatory condition following an infection with Group A Beta Hemolytic Streptococcus (GABHS), in which the heart is attacked by antibodies formed in reaction to a recent GABHS infection. "In rheumatic heart disease, miR‐155 aggravated the valve injury through S1PR1, SOCS1/STAT3 and IL‐6/STAT3 signalling pathways." (PMID 33664937, 2021).
rhinosinusitis (1 paper, 2022). "However, STING represses IL-13-induced STAT6 phosphorylation in subjects with rhinosinusitis by increasing expression of the STAT6 inhibitor SOCS1 (suppressor of cytokine signaling 1)." (PMID 35281022, 2022).
Sciatica (1 paper, 2021). Pain in the lower back and hip radiating in the distribution of the sciatic nerve. "The roles of SLC8A1, RBM20, GPER1, IL27, SOCS1, and GRTP1-AS1 in sciatica or in relieving sciatica are currently unknown." (PMID 33573686, 2021).
skin tumors (1 paper, 2017). "In both skin tumors, a high number of infiltrating immune cells expressing SOCS1 was detectable." (PMID 28445952, 2017). "Next, we analyzed SOCS3 and SOCS1 levels in SCC and BCC skin tumor lines left untreated or stimulated with IL-22." (PMID 28445952, 2017). "To this end, we analyzed the in vivo expression of SOCS3 and SOCS1 in BCC or SCC skin tumor specimens, including lesional (LS) and non-lesional (NLS) zones." (PMID 28445952, 2017).
spondylitis (1 paper, 2020). The inflammation of a vertebra. "Correlation between DNA methylation of SOCS1 and the degree of inflammation, assessed by TNFα and IL-6 levels, was also shown in patients with HLA-B27+ spondylitis." (PMID 32670294, 2020).
Streptococcus pneumonia (1 paper, 2023). "In neutrophils treated with VitD3 and infected with Streptococcus pneumonia, there is increased expression of SOCS-1 and SOCS-3 compared to non-treated neutrophils." (PMID 35850625, 2023).
Thrombocytopenia (1 paper, 2017). A reduction in the number of circulating thrombocytes. "It was found that the SLE patients have a lower frequency of SOCS1-1478del compared with those SLE patients without thrombocytopenia, suggesting that genetic background influences specific hematologic abnormalities in patients with SLE through regulating SOCS1 gene expression." (PMID 29085365, 2017).
Thrombocytosis (1 paper, 2025). Increased numbers of platelets in the peripheral blood. "Consistent with our findings, Navarro, Pairet also identified a targeting relationship between miR-221-3p and SOCS1 in patients with thrombocytosis." (PMID 41002956, 2025).
thyroid cancer (1 paper, 2020). "Given the oncogenic nature of JAK/STAT pathway in different human cancers including thyroid carcinomas, targeting miR-155 could inhibit the thyroid cancer development/progression via activating SOCS1 and suppressing JAK/STAT." (PMID 33158279, 2020).
viral hepatitis (1 paper, 2022). An acute or chronic inflammation of the liver parenchyma caused by viruses. "The SOCS1 and SOCS3 proteins are involved in immune response and inhibit protective interferon signaling in viral hepatitis." (PMID 35626153, 2022).
tumor (304 papers, 2003 to 2025). "The dysregulation of this pathway, particularly through SOCS-1, has been associated with more aggressive tumor phenotypes." (PMID 39859246, 2025). "A loss of SOCS1 also contributes to immune evasion by cancer cells, as this pathway is involved in modulating the immune response against tumor cells." (PMID 40427514, 2025). "Cancer susceptibility candidate 2 (CASC2) acts as a tumor suppressor by targeting miR‐155, restoring suppressors of cytokine signaling 1 (SOCS1) expression and inhibiting HCC proliferation." (PMID 40693828, 2025). "Certain genes, such as SOCS-1, are associated with anoikis, and silencing SOCS-1 can inhibit subcutaneous tumor growth and metastatic development in the lungs in vivo." (PMID 40331942, 2025). "In contrast, activation related to SOCS1 was associated with tumor progression and reduced survival rates." (PMID 40005948, 2025). "Inhibition of SOCS1 in T cells can boost antitumor immunity, whereas its loss in tumor cells increases tumor aggressivity." (PMID 38415248, 2024). "In such SOCS1-deficient tumors, drugs that lower antioxidant defenses would be helpful in increasing sensitivity to drugs that mediate tumor killing by increasing ROS production." (PMID 38254783, 2024). "Our analysis revealed that elevated SOCS1 expression is associated with increased immune scores and reduced tumor purity, similar to most immune checkpoints." (PMID 39654174, 2024). "Mechanisms underlying the tumor suppressing activity of SOCS1 likely involve the regulation of multiple cancer-cell-signaling pathways." (PMID 38254783, 2024). "In contrast, another study demonstrated that SOCS1 deficiency slowed tumor development by increasing antitumor inflammation." (PMID 37009803, 2023). "Recent findings have suggested that SOCS1 is a tumour suppressor, and its downregulation has been implicated in cancer progression." (PMID 35610596, 2022). "Consistent with our observation, previous research indicates Socs1 loss relates to inflammation-associated tumor development." (PMID 36505769, 2022). "The downregulation of IFN-I signaling under tumor conditions leads to the downregulation of SOCS1, which causes the activation of the PI3K-Akt/mTOR pathway." (PMID 35013108, 2022). "Regarding cancer-cell–intrinsic SOCS1 expression, previous studies have identified Socs1 as a gene associated with immunosuppression and tumor progression." (PMID 31133614, 2019). "Compared to wild type BMDCs, SOCS1-deficient BMDCs induce stronger T-helper 1 cells (Th1) responses and more effective anti-tumor immunity in vivo." (PMID 30658461, 2019). "Suppressor of cytokine signaling 1 (SOCS1) is a postulated tumor suppressor gene associated with growth arrest of tumor cells, rapid dephosphorylation of JAK2, and silencing of cyclin D1." (PMID 30884772, 2019). "The expression of SOCS1 reduces in various human cancers and is tightly associated with tumor angiogenesis." (PMID 30285793, 2018). "When the respective phosphorylation sites were mutated in SOCS-1 or SOCS-3, BCR-ABL induced tumor formation was completely blocked in nude mice due to “activation” of SOCS-1 or SOCS-3." (PMID 28753604, 2017). "This study extends the emerging paradigm of JAK3 activating mutations to CTCL and further implicates SOCS1 in the control of lymphomatous signaling, thus widening the number of potentially actionable targets in affected neoplasms." (PMID 27144517, 2016). "SOCS1 appears to have tumor suppressor activity and restoration of SOCS1 gene expression causes growth suppression and induction of apoptosis in HCC cells." (PMID 25849377, 2015).